PPARG (peroxisome proliferator activated receptor gamma)
Diseases named in the same sentence as PPARG in open-access papers (continued):
Sharing a sentence is not in itself a finding about the gene and the disease.
type 2 diabetes (continued). "Pioglitazone is an agonist of peroxisome proliferator-activated receptor gamma (PPARγ) and a known insulin sensitizer, primarily used to treat type 2 diabetes." (PMID 38078368, 2024). "Firstly, we have shown that the PPARG promoter is hypermethylated in obese and type 2 diabetic patients, which correlates with the downregulation of the expression of numerous genes responsible for proper insulin signal transduction in adipocytes." (PMID 39595621, 2024). "PPARγ agonists (thiazolidinediones) improve insulin sensitivity and are used in the therapy of Type 2 diabetes." (PMID 36768666, 2023). "TZD class PPARG agonists have been widely used clinically as insulin sensitizers to treat type 2 diabetes." (PMID 37569334, 2023). "The fifth co-cited reference proved that applying pioglitazone as agonists of peroxisome proliferator-activated receptor gamma (PPAR gamma) can reduce the incidence of macrovascular events in patients with type 2 diabetes." (PMID 36950100, 2023). "Lobeglitazone, a type of thiazolidinedione (TZD), is a peroxisome proliferator-activated receptor gamma (PPARγ) ligand used to regulate glucose and lipid metabolism in type 2 diabetes." (PMID 37616215, 2023). "Previous studies had shown PPARG activation improved the angiogenic potential, proliferation, and migration of EPCs which are impaired in type 2 diabetes." (PMID 37057206, 2023). "This intricate interplay between PPARγ and bone metabolism becomes evident when examining thiazolidinediones (TZDs), which is a drug class prescribed for type 2 diabetes." (PMID 37892460, 2023). "Pioglitazone is a well-known PPARγ agonist and an approved drug for the treatment of type 2 diabetes that enhances PPARγ expression." (PMID 37373253, 2023). "The thiazolidinedione class of PPARγ agonists, including rosiglitazone and pioglitazone, are used in the treatment of type 2 diabetes by improving insulin sensitivity." (PMID 36928191, 2023). "PPARδ is the less studied receptor of this group while PPARα and PPARγ have been extensively investigated as therapeutic targets especially in metabolic diseases like type 2 diabetes (T2D)." (PMID 36176461, 2022). "Thiazolidinediones (TZDs) are PPARγ synthetic ligands with insulin-sensitizing properties, used for the treatment of type 2 diabetes." (PMID 36358540, 2022). "Thiazolidinediones (TZD) improve insulin sensitization and glucose homeostasis mediated by the activation of peroxisome proliferator-activated receptors γ (PPARγ) in patients with type 2 diabetes." (PMID 37746194, 2022). "Recent research has demonstrated that Type 2 Diabetes (T2D) risk is influenced by a number of common polymorphisms, including MC4R rs17782313, PPARG rs1801282, and TCF7L2 rs7903146." (PMID 35292917, 2022). "Activation of PPARγ by thiazolidinediones, high-affinity agonists for PPARγ, lowers arterial pressure and exerts vasoprotective effects in patients with type 2 diabetes enrolled in the PROactive trial of pioglitazone." (PMID 35358093, 2022). "In EPCs isolated from type 2 diabetic patients there is an inhibition of STAT5/PPARγ transcriptional complex, leading to inactivation of Cyclin D1 and cell cycle arrest." (PMID 36176980, 2022). "It is well known that pioglitazone as a PPARγ agonist can enhance insulin sensitivity for type 2 diabetes but adversely affects body composition and bone metabolism." (PMID 36547073, 2022). "Pioglitazone hydrochloride (PGZ), which is a peroxisome proliferator-activated receptor gamma (PPAR-γ) agonist, is widely used as an oral drug for the treatment of hyperglycemia in type 2 diabetes." (PMID 35677109, 2022). "Pioglitazone is an anti-inflammatory insulin sensitizer widely used to treat hyperglycemia in type 2 diabetes via activation of peroxisome proliferator-activated receptor gamma (PPAR-γ)." (PMID 35431893, 2022).
type 2 diabetes (continued). "Systemic administration of PPARγ agonists thiazolidinediones (TZDs) in type 2 diabetes improves glucose homeostasis in human and animal models through improved insulin sensitivity." (PMID 36568082, 2022). "The specific agonists of PPARγ, i.e., TZDs, are clinical drugs currently on the market as insulin sensitizers for the treatment of type 2 diabetes, targeting PPARγ to exert a hypoglycemic effect." (PMID 36611922, 2022). "Severe hyperglycemia has been discerned in individuals with the dominant-negative PPARG genetic defect, suggesting a biological link between type-2 diabetes and the PPARG gene." (PMID 35207564, 2022). "A better understanding of PTMs of PPARγ will help to design a new generation of safer compounds targeting PPARγ to treat type 2 diabetes." (PMID 36551260, 2022). "The demonstration of presence of these variants also warrants their detection in kidney biopsies from patients treated with PPARγ agonists for diabetic nephropathy or type II diabetes." (PMID 36359851, 2022). "PPARγ agonists such as thiazolidinediones (TZDs) have been used in type 2 diabetes treatment to increase insulin sensitivity." (PMID 36339572, 2022). "It has been shown that combined treatment with a drug used to treat type 2 diabetes (pioglitazone) and apha-galactosylceramide induces lipid synthesis via PPARγ activation and significantly enhances iNKT cell-mediated antitumor immune response." (PMID 35406621, 2022). "Pioglitazone is a synthetic PPARγ agonist and is the first-line drug for the clinical treatment of type 2 diabetes." (PMID 35517804, 2022). "In conclusion, the present study has shown for the first time that baccharin enhances adipocyte differentiation via PPARγ activation in a cell model and that baccharin administration reduces blood glucose levels in the ob/ob mouse model of type 2 diabetes." (PMID 34203569, 2021). "The non-CHD indications of clinically used drugs included dyslipidemias (PPARA), type 2 diabetes (PPARG and NDUFA13), autoimmune diseases (TNF), neoplasms (RAF1 and PSMA5), circulatory disorders (ABCA1, PLG, ITGB3, and F2), and alcohol-dependency (ALDH2)." (PMID 34675202, 2021). "Used as an antidiabetic drug in type 2 diabetes patients, Pioglitazone is a peroxisome proliferator-activated receptor gamma (PPAR-γ) agonist." (PMID 34638304, 2021). "Many exogenous peroxisome proliferators (PP) are agonists of PPAR, as evidenced by the fact that PPARγ and PPARα are respective molecular targets for the type 2 diabetes drug thiazolidinediones (TZDs) and for dyslipidemia drug fibrates." (PMID 34681767, 2021). "Glitazones, agonists of peroxisome proliferator-activated receptor-gamma (PPARγ) nuclear receptors, are approved for glycemic control in patients with type 2 diabetes." (PMID 34858740, 2021). "The unusual ligand-binding properties of PPARγ are well-known and used in the treatment of type 2 diabetes and other metabolic disorders." (PMID 34679887, 2021). "NAC-treated PSCs had a quiescent-like state that was maintained by coadministration of NAC and Pioglitazone, a ligand of peroxisome proliferator-activated receptor gamma (PPARγ) which used for type II diabetes previously." (PMID 33858491, 2021). "A deeper knowledge of PPARγ physiological role will contribute to better understand the functionality of these PPARγ agonists on preventing type 2 diabetes." (PMID 34887761, 2021). "In contrast, the tesaglitazar and the glitazar classes of dual PPARα and PPARγ agonists has been shown to worsen cardiac function in type 2 diabetes patients." (PMID 34360540, 2021). "PPARγ is indeed the best-characterized target of the insulin-sensitizers of the thiazolidinedione family used in the treatment of type 2 diabetes, and its use as a therapeutic anti-cancer target is also a matter of debate." (PMID 33846376, 2021). "Pioglitazone, an agonist of peroxisome proliferator-activated receptor gamma, was habitually used for type II diabetes, but recently reported to inhibit metastasis of PCCs." (PMID 33858491, 2021).
type 2 diabetes (continued). "Because of this, PPARγ antagonists have been seen as a potential therapy for type 2 diabetes and obesity." (PMID 35003101, 2021). "The PPARγ agonist rosiglitazone, an approved drug for type 2 diabetes, exerts inhibitory effects on pituitary tumour growth, tumour ACTH synthesis, and secretion." (PMID 33491272, 2021). "Because of these critical roles played by PPARγ, a large effort has been invested in developing synthetic ligands specific to PPARγ, which can reverse various disease states, including type 2 diabetes, inflammation, and cancer." (PMID 34339734, 2021). "For example, both miR-192 and miR-20b target components of peroxisome proliferator activated receptor gamma (PPARG), which is located in the Type II diabetes mellitus pathway." (PMID 34425916, 2021). "This indicates further that drugs like pioglitazone, widely used in the treatment of type 2 diabetes, can influence GABARα2 expression via the PPARγ/PGC-1α system." (PMID 33597848, 2021). "PPARα agonists such as fibrates have long been clinically used to treat hypertriglyceridemia, whereas PPARγ agonists, such as thiazolidinediones, are approved for type-2 diabetes (T2D)." (PMID 34681249, 2021). "The thiazolidinedione (TZD) class of drugs, peroxisome-proliferator-activated receptor gamma (PPARγ) activators, was approved more than 20 years ago, and is the only insulin-sensitizing medication for the treatment of type 2 diabetes." (PMID 34832978, 2021). "Due to the potential usefulness of activators of PPARγ as a therapeutic option for type 2 diabetes, it is important to understand the relationship of PPARγ with type 2 diabetes related traits." (PMID 34887761, 2021). "The nuclear transcription factor PPARγ has been established as a target in type 2 diabetes for many years." (PMID 32522977, 2020). "Another group reported that a PPARγ agonist enhanced the therapeutic effects of MSCs in the type 2 diabetes model through a decrease in plasma glucose levels." (PMID 32652045, 2020). "Treatment with the thiazolidinedione class of peroxisome proliferator-activated receptor gamma (PPARγ) agonists, widely prescribed for treating type II diabetes mellitus, have been shown to significantly improve memory and cognition in patients with AD." (PMID 32392803, 2020). "The transcriptional factor peroxisome proliferator–activated receptor γ (PPARγ) is an important therapeutic target for the treatment of type 2 diabetes." (PMID 32973516, 2020). "PPARγ agonists such as rosiglitazone are used as insulin-sensitizing agents to treat type 2 diabetes." (PMID 33776749, 2020). "The intracellular signaling pathways mediated by PPARγ have been considered therapeutic targets for type 2 diabetes and Alzheimer’s disease." (PMID 32266936, 2020). "The family of thiazolidinediones is widely used to activate PPARγ in the treatment of type II diabetes." (PMID 32260486, 2020). "The antifibrotic and renoprotective effects of the PPARγ agonists pioglitazone and troglitazone were also confirmed in type 2 diabetes (T2D) rat models and unilateral ureteral obstruction (UUO) mice models, respectively." (PMID 32158560, 2020). "Peroxisome proliferator-activated receptor-gamma (PPARγ) is a transcription factor drugable by agonists approved for treatment of type 2 diabetes, but also inhibits carcinogenesis and cell proliferation in vivo." (PMID 32522977, 2020). "Rosiglitazone (RGZ) and other thiazolidinedione (TZD) synthetic ligands of PPARγ are insulin sensitizers that have been used for the treatment of type II diabetes." (PMID 32272794, 2020). "A study found that individuals with PPARγ deletions suffer from early-onset type II diabetes accompanied with severe IR." (PMID 32272794, 2020). "PPARα and PPARγ agonists are already in clinical use for the treatment of hyperlipidemia and type 2 diabetes, respectively." (PMID 33126411, 2020).
type 2 diabetes (continued). "Thiazolidineodiones, or simply “glitazones,” belong to a class of compounds that activates PPARγ and can be employed to treat type 2 diabetes and metabolic syndrome." (PMID 31555078, 2019). "Thiazolidinediones (TZDs), a class of peroxisome proliferator-activated receptor-gamma (PPAR-γ) agonists, can improve insulin sensitivity and lower blood glucose level for patients with type 2 diabetes." (PMID 31639149, 2019). "Rosiglitazone and other synthetic ligands of PPARγ have been used as insulin sensitizers for the treatment of type 2 diabetes." (PMID 30845932, 2019). "As such, FDA-approved drugs that activate PPARγ are highly effective for treating type-2 diabetes in the form of the thiazolidinediones (TZDs) pioglitazone (ActosTM) and rosiglitazone (AvandiaTM; GlaxoSmithKline plc., Brentford, United Kingdom)." (PMID 30930764, 2019). "Some reports have indicated that the methylation of Pparγ promoter changes in metabolic disorders, especially type 2 diabetes." (PMID 31883537, 2019). "Pioglitazone, a peroxisome proliferator-activated receptor gamma (PPAR-γ) agonist, is widely used to treat hyperglycaemia in type 2 diabetes." (PMID 30867485, 2019). "Synthetic PPARγ agonists (thiazolidinediones or glitazones) have been used clinically in the treatment of type II diabetes." (PMID 31159430, 2019). "These functions make PPARγ a therapeutic target for type 2 diabetes and other metabolic diseases such as obesity and atherosclerosis." (PMID 31137814, 2019). "Peroxisome proliferator-activated receptor gamma (PPARγ) agonists are used for the treatment of type 2 diabetes and metabolic syndrome." (PMID 31240205, 2019). "The effects of PPARγ agonists, known for their positive activity on type II diabetes mellitus, have been explored and present promising effects in the control of neuropathic pain, including CINP, and also cancer." (PMID 31555078, 2019). "Thiazolidinediones (TZDs), a class of drugs that are derivatives of thiazolidinedione, are selective activators of PPARγ and are widely used to treat type 2 diabetes (T2DM)." (PMID 31336903, 2019). "Thiazolidinedione (TZD), a known full PPARγ agonist, has been used for the treatment of type 2 diabetes, however its use has been limited because of adverse effects such as body weight gain and edema." (PMID 31137814, 2019). "Peroxisome proliferator-activated receptor γ (PPARγ) is a major therapeutic target for the treatment of type 2 diabetes." (PMID 31371757, 2019). "While PPARγ agonists and most of PPARγ target genes are proven protection in type 2 diabetes and cardiovascular diseases, a minority of PPARγ target genes, such as CD36, are reported to promote VSMC proliferation and tumor metastasis." (PMID 31253783, 2019). "We also found opposite situations that PPARγ was expressed lower in the liver of a rat model of type 2 diabetes or in white adipose tissue of high-fat diet-induced obese mice." (PMID 31019978, 2019). "Targeting peroxisome proliferator-activated receptor γ (PPARγ) by synthetic compounds has been shown to elicit insulin sensitising properties in type 2 diabetics." (PMID 30906767, 2018). "Accumulating evidence indicates that PPARγ is a potential therapeutic target not only for the treatment of type II diabetes and inflammation but also for cancer." (PMID 30018246, 2018). "In turn, STAT5A was shown to be involved in adipocyte differentiation probably by controlling the expression of PPARγ, and type 2 diabetic patients had decreased expression of both PPARγ and STAT5A genes." (PMID 29977307, 2018). "From metabolic disease, the resolution of insulin resistance by PPARγ and combined PPARα/γ agonists, as well as long-term outcome in patients with type II diabetes, we learned a lot on simultaneous PPARα/γ stimulation." (PMID 30424016, 2018).
type 2 diabetes (continued). "Rosiglitazone (RG) is a well-known activator of peroxisome proliferator-activated receptor-gamma (PPARγ) and used to treat hyperglycemia and type 2 diabetes; however, its clinical application has been confounded by adverse side effects." (PMID 30627576, 2018). "Fibrates are PPARα agonists used to treat dyslipidemia, thiazolidinediones (TZDs) are PPARγ agonists used to treat type 2 diabetes, and the glitazars are dual PPARα and PPARγ agonists used to treat dyslipidemia and type 2 diabetes comorbidities." (PMID 30283300, 2018). "Valsartan and Telmisartan were tested in type II diabetes with immune effects, perhaps binding to Peroxisome Proliferator-Activated Receptor Gamma (PPAR-γ), and Valsartan is able to slow down the progression of chronic kidney disease." (PMID 30288187, 2018). "Originally, thiazolidinediones (TZDs), synthetic PPARγ activators, have been used for the treatment of patients with type II diabetes through modulating PPARγ-targeted genes including cyclin D1, inflammatory cytokines, and NF-κB." (PMID 30018246, 2018). "Later on, it was confirmed that swertiamarin 63 can be used to treat type II diabetes mellitus because it can regulate the peroxisome proliferator-activated receptor gamma (PPAR-γ) and increases insulin sensitivity." (PMID 30304864, 2018). "Although the use of TZDs has strongly declined due to their side effects, PPARg remains a promising target in the prevention and treatment of type 2 diabetes as highlighted by ongoing basic and clinical research." (PMID 29973382, 2018). "Thiazolidinediones (TZDs), also called glitazones, are synthetic agonists of the peroxisome proliferator-activated receptor gamma (PPARγ) nuclear receptor with potent anti-diabetic efficacy in patients with type 2 diabetes." (PMID 30575522, 2018). "RG is a full agonist of PPARγ, activates the PPARγ nuclear receptor, and is widely used as a therapeutic agent for type 2 diabetes." (PMID 30627576, 2018). "For example, bexarotene and alitretinoin (RXRs), fibrates (PPARα), and thiazolidinediones (PPARγ) are drugs approved for treating cancer, hyperlipidemia, and type 2 diabetes, respectively." (PMID 30148160, 2018). "In particular, miR-130 was reported to be downregulated in mice fed an obesogenic diet and in adipocytes of obese and type 2 diabetic patients, who also have high levels of PPARγ in adipose tissues and a low abundance of preadipocytes." (PMID 28167956, 2017). "Glitazones are known for their antidiabetic action and belong to a group of synthetic compounds which act as agonists of PPARγ and improve insulin sensitivity and reduce the blood glucose levels in patients with type 2 diabetes." (PMID 28656106, 2017). "PPARγ is a target for thiazolidinedione (TZD) class of drugs which are widely used for the treatment of type 2 diabetes." (PMID 29203903, 2017). "We and others have previously presented evidence of exercise’s potential to combat—via such redox-sensitive PPARγ/LXRα signalling—the pathogenesis of numerous chronic inflammatory diseases including type-2 diabetes, hypertension, and atherosclerosis." (PMID 28796154, 2017). "Pharmacology and chemistry of thiazolidinediones as PPARγ agonists and the potential of newer analogues as dual agonists of PPARs and other emerging targets for the therapy of type 2 diabetes are presented." (PMID 28656106, 2017). "Their data sheds new light to the regulation of PPARγ and another alternative to the treatment of Type 2 Diabetes." (PMID 28243251, 2017). "As a consequence of the improvement in insulin sensitivity, PPARγ activation by thiazolidinediones decreases glycated hemoglobin (HbA1c) and lowers the glucose and insulin levels in patients with type 2 diabetes." (PMID 28656106, 2017). "Synthetic ligands/agonists of PPARγ, e.g. thiazolidinediones, commonly used as insulin sensitizers for treating hyperglycemia in patients with type II diabetes, are of great clinical significance." (PMID 28570659, 2017).